CAT (catalase)
Diseases named in the same sentence as CAT in open-access papers (continued):
Sharing a sentence is not in itself a finding about the gene and the disease.
hypothyroidism (17 papers, 2005 to 2025). Abnormally low levels of thyroid hormone. "Based on this study, 400 mg/kg of TQ improved liver damage associated with hypothyroidism by over-expression of the antioxidant CAT gene." (PMID 34867384, 2021). "In conclusion, increased serum TSH and MDA concentrations, in addition to decreased serum T4 and fT4 concentrations and decreased SOD and CAT activities, indicated that there was oxidative stress in dogs with hypothyroidism." (PMID 40256603, 2025). "On the other hand, overt hypothyroidism is associated with increased oxidative stress, as plasma SOD and CAT were significantly elevated in hypothyroid patients compared to healthy controls and were significantly associated with elevated levels of TSH." (PMID 40256603, 2025). "In the thyroid and other organs, the inflammation (edema, vascularization, and infiltration) observed during hypothyroidism has been explained by the low expression of antioxidant thyroid-dependent enzymes such as catalase (Cat) and glutathione peroxidase." (PMID 37834351, 2023). "Along with that, hypothyroidism induced more intense cytoplasmic localization of CAT starting from the 15th day of methimazole treatment (Figure 3C3,C4)." (PMID 33921249, 2021). "Namely, we showed that hypothyroidism increased protein expression of AD enzymes (CuZnSOD, MnSOD, CAT, GCL, Trx, and total GSH content) and TR and CAT activity in BAT." (PMID 33921249, 2021). "The degree of peroxisomal CAT immunogold positivity increases over the time course of hypothyroidism and largely depended on the method of peroxisomal biogenesis." (PMID 34571897, 2021). "The reported results regarding CAT levels in hypothyroidism compared with controls are contradictory as well." (PMID 30467493, 2018). "OS parameters were significantly higher in hypothyroidism, with significantly lower levels of antioxidant activity (CAT; p = 0.03) and significantly higher levels of oxidants (TBARS; p = 0.03)." (PMID 30467493, 2018). "In our prospective study, we have demonstrated a significantly lower CAT activity in hypothyroidism which was improved after achieving euthyroidism by levothyroxine replacement." (PMID 30467493, 2018). "Using both DAB- and CAT-labelled peroxisomes to study their origin and maturation, we found that canonic and de novo pathways of peroxisomal biogenesis take place in both euthyroid control and over the time course of hypothyroidism." (PMID 34571897, 2021). "Thymoquinone significantly (p < 0.001) upregulated catalase transcription by about 24-fold and could block the hypothyroidism-induced glomerular and tubular injury." (PMID 32774669, 2020). "Thymoquinone may have a potential protective effect against hypothyroidism-induced renal injury acting through the attenuation of the oxidative stress and upregulation of renal catalase gene expression." (PMID 32774669, 2020). "Some reported higher but some lower CAT activity in patients with hypothyroidism." (PMID 30467493, 2018). "When CAT activity is reduced in hypothyroidism, a possible excessive H2O2 in an organism could react with NO, producing peroxynitrite radicals or other hydroxyl radicals." (PMID 30467493, 2018). "For example, the localization of AD enzymes in peroxisomes, MnSOD in particular, and the continued increase in peroxisomal CAT protein expression during hypothyroidism could indicate a synergistic response of redox remodeling and the remodeling of oxidative processes." (PMID 33921249, 2021). "Conversely, SOD, CAT, and GSH-px were all significantly reduced in hypothyroid persons, and there was a reduction in antioxidative defense in patients with hypothyroidism." (PMID 40256603, 2025). "The activity of different brain antioxidant enzymes (GSH, GPx, SOD, and catalase) was evaluated in irradiated and unirradiated PTU hypothyroidism-induced rats." (PMID 37368180, 2023). "Based on SOD, CAT, GSH-px, and MDA, dogs with hypothyroidism had oxidative stress." (PMID 40256603, 2025).
hypothyroidism (continued). "Treatment with Kp10, in turn, reduced testicular apoptosis and the production of peroxynitrite, while increased SOD1 and GPX 1⁄2 expression, and enzymatic activity of CAT, but did not affect the lower expression of UPR mediators caused by hypothyroidism." (PMID 38338793, 2024). "Hypothyroidism induced by PTU significantly increased AST, ALT, ALP, creatinine, BUN, and MDA concentration and noticeably reduced albumin, total protein, total thiol level, and SOD and CAT activity." (PMID 37144592, 2023). "The hypothyroidism rats that received MEE showed a notable decline in the brain MDA and NO levels coupled with significant enhancement in the levels of GSH and activities of GPx, SOD, and catalase as compared with the PTU and PTU+IR groups." (PMID 37368180, 2023). "Conversely, hypothyroidism induced a strong decrease in Pex6 protein expression, which did not affect catalase import, as we demonstrated by CAT immunogold labelling." (PMID 34571897, 2021). "In this respect, the counteraction by Q of MMI-induced SOD, but not CAT, activity has been reported in the liver of rats experimentally treated to develop hypothyroidism." (PMID 34679050, 2021). "IR-induced damage is ameliorated by spin traps, inhibition of inducible nitric oxide synthase, lecithinized superoxide dismutase (SOD), ebselen, a ONOO- scavenger, inhibitors of calpain activation, SOD and catalase (CAT) mimetic, antioxidants, or in the other circumstances such as hypothyroidism." (PMID 16274486, 2005). "Indeed, hypothyroidism decreases metabolism and reduced synthesis and activities of SOD and CAT." (PMID 40256603, 2025). "A specific cytochemical DAB staining technique and immunogold labelling of catalase (CAT), as a peroxisomal marker, were used to identify peroxisomes and analyze peroxisomal proliferation and maturation in rat brown adipocytes over the time course of hypothyroidism." (PMID 34571897, 2021). "Both states of thyroid dysfunction (hyperthyroidism and hypothyroidism) promote oxidative damage in brain tissues displayed by elevated levels of MDA and NO concomitant with depletion of the enzymatic (SOD, CAT, and GPx) and non-enzymatic (GSH) antioxidants leading to brain damage." (PMID 37368180, 2023).
liver cancer (17 papers, 2013 to 2024). An epithelial or non-epithelial malignant neoplasm that arises from the liver. "Bai and Cederbaum, in their study, showed that catalase protects human HepG2 liver cancer cells from apoptosis caused by the administration of DNA-damaging cytostatics." (PMID 38068888, 2023). "As summarized elsewhere, hydrodynamic transfection of MET/CAT with SB is a reliable and widely used method to generate liver cancer in mice." (PMID 37078828, 2023). "We then took an intersection of the Kcr proteins identified in liver cancer tissue quantitative analysis and hypoxic cell lines: CAT, S100A8, EEF2, and LMNA were co-identified." (PMID 35977926, 2022). "Meanwhile, relatively high catalase protein levels accompanied by relative high catalase enzyme activities were observed in HepG2, Huh7 and Hep3B liver cancer cells." (PMID 34676172, 2021). "Together, these results indicate that the NQO1:CAT ratio is an ideal therapeutic window in liver cancer for NQO1 bioactivatable drugs." (PMID 34676172, 2021). "Pathophysiologically, the initiation of hepatic cancer in these models is induced by decreased mRNA expression of GPx, CAT and GST." (PMID 29621129, 2018). "We further tested the relationship between ROS and HBx levels by transiently transfecting Huh7 liver cancer cells with the HBx gene and found that HBx levels in these cells were also significantly reduced by MnSOD or catalase." (PMID 25361011, 2014). "Previous studies have shown that CAT decreases metastasis in liver cancer." (PMID 29755559, 2018). "Furthermore, the data presented in this study reveal that NQO1 and the NQO1:CAT ratio could be used as biomarkers to examine the efficacy of NQO1 bioactivatable drugs in HCC or other kinds of liver cancers." (PMID 34676172, 2021). "A study revealed that notopterol downregulated the expression levels of p-JAK2, ATF4, glutathione peroxidase 1 (GPX1), catalase (CAT), and superoxide dismutase 1(SOD1) proteins in liver cancer cell lines, thereby reducing the proliferation and invasion capabilities of cancer cells." (PMID 39770441, 2024). "Whether the crotonylation of CAT, S100A8, and EEF2 plays a vital role in liver cancer proliferation and the cellular response to hypoxia remains to be investigated." (PMID 35977926, 2022). "To investigate whether the NQO1:CAT ratios are a potential therapeutic window in liver cancer, we analyzed NQO1 and CAT expression in liver hepatocellular carcinoma (LIHC) from The Cancer Genome Atlas (TCGA)." (PMID 34676172, 2021). "A previous in vitro study showed that treatment of ginger extract on liver cancer cell line removed the superoxide radicals and hydrogen peroxide by replacing the function of glutathione peroxidase (GPx), superoxide dismutase (SOD), and catalase (CAT)." (PMID 32419792, 2020).
neuropathy (17 papers, 2012 to 2025). A disorder affecting the nervous system that manifests with pain, tingling, numbness, and/or muscle weakness. "GPx can prevent activation of peroxisome-bound catalase, supporting the concept of mitochondrially-derived ROS in paclitaxel-induced painful neuropathy, with GPx preventing hydrogen peroxide-induced cell death." (PMID 27393249, 2016). "Accordingly, in the rat model of oxaliplatin-induced neuropathy a similar alteration of catalase is highlighted in DRGs and spinal cord." (PMID 25036594, 2014). "A genetic predisposition to oxidative stress and an increased risk in neuropathy due to polymorphism of antioxidant enzymes like superoxide dismutase (SOD), glutathione peroxidase (GPX), and catalase (CAT) has been demonstrated in a diabetic population." (PMID 25520703, 2014). "This extract also showed significant antioxidation activities by reducing lipid peroxidation, increasing superoxide dismutase level, elevating the reduced glutathione (GSH), as well as by increasing catalase activity in different animal models of neuropathy and neuropathic pain." (PMID 36382046, 2022). "Additionally, a cisplatin-induced neuropathy model affected catalase levels protected by co-administration of melatonin, revealing its potent antioxidant activity." (PMID 35893792, 2022). "The antioxidant potentials of AS, FKCA, and KRA on elevating CAT and GSH, and reducing LPO levels, propose their potentials in ameliorating painful-neuropathy." (PMID 31143690, 2019). "It is believed that the neuropathy model used in this study may have induced an increase in lipid peroxidation, followed by a compensatory decrease in the activities of SOD, CAT and GPx." (PMID 38507417, 2024). "Similarly, in vincristine-induced neuropathy, advanced formulations like curcumin nano-emulsions significantly reduce cold and thermal hyperalgesia by boosting antioxidant (SOD, CAT) and anti-inflammatory (IL-10) markers, while downregulating NF-κB expression in the sciatic nerve." (PMID 41425625, 2025). "Nitrosative and oxidative reactions may also play a role in neuropathy development, as evidenced by significant increases in nitrite and MDA levels in nerve tissue following VCR administration, along with decreased levels of GSH, SOD, and CAT." (PMID 37107178, 2023). "A significant decrease of SOD (P < 0.05), GPX (P < 0.05) and nonsignificant decrease of CAT (P > 0.05), and TAS status (P > 0.05) were seen in T2DM patients with neuropathy compared to T2DM patients as well as controls." (PMID 22718504, 2012).
bladder cancer (16 papers, 2009 to 2025). "On the other hand, a study was performed on paraffin-embedded tissues (obtained from 75 bladder cancers and 30 normal bladders) that were treated with immunohistochemical staining for catalase, superoxide dismutase and glutathione peroxidase." (PMID 30042310, 2018). "Although we validated this interaction and established the existence of mutual interaction between Parkin and USP30 in BLCA cells, it remains unclear whether USP30 is involved in the Parkin-mediated regulation of catalase in bladder cancer." (PMID 38424181, 2024). "In thyroid cancer cells, 1 mM (176 μg/mL) vitamin C showed toxic effects, being reported to inhibit the activity of catalase and SOD in ARO, or it can lead to formation of a large amount of ROS and cause the cell cycle arrest of human bladder carcinoma T24 cells and Ehrlich carcinoma cells." (PMID 37176085, 2023). "Lowered SOD, CAT, and GPx activity are characteristic of bladder cancer." (PMID 34822465, 2021). "Similarly, WFA upregulates the mRNA expression of antioxidant genes (NFE2L2, CAT, SOD1, TXN, GSR, NQO1, and HMOX1) in bladder cancer cells associated with oxidative stress generation." (PMID 34209212, 2021). "In bladder cancer, TRMP8 also regulates ROS production and the expression levels of the enzymes Catalase, HO-1, and SOD2, which regulate tumor growth in vivo, demonstrating that TRPM8 has an essential role in bladder cancer." (PMID 37033630, 2023). "Rhamnolipids exhibit cytotoxicity against leukemic, cervical, breast and bladder cancer cells, disrupt the biofilm formation in dairy, eliminate the oxidative stress by activating antioxidant enzymes (SOD, CAT and GR), and fold the outer membrane protein OmpA." (PMID 33397389, 2021). "Our results clearly showed that PPM-18 remarkably promoted ROS production in bladder cancer cells, in accompany with the altered expression of antioxidant proteins, such as SOD1 and catalase." (PMID 34305598, 2021). "As shown here, BRP treatment increased the mRNA levels of the antioxidant enzymes CAT, Cu/Zn-SOD, TRx, GST, and Mn-SOD in a bladder cancer cell line." (PMID 25530785, 2014). "A study on bladder cancer indicates that Parkin influences bladder cancer progression and metastasis by regulating cellular ROS levels through ubiquitin-mediated proteasomal degradation of Catalase, rather than its autophagic function." (PMID 38424181, 2024). "In conclusion, our study revealed that CAP could suppress proliferation and induce cell cycle arrest as well as ROS production possibly via FOXO3a-mediated pathways in bladder cancer cells, whereas no obvious cell apoptosis under the protection of increased catalase and SOD2 enzymes." (PMID 27775662, 2016).
coronary artery disease (16 papers, 2017 to 2025). "Notably, epidemiological studies have convincingly shown that higher circulating concentrations of the antioxidant enzymes GPx, SOD, and catalase are associated with a significant reduction in the risk of coronary heart disease." (PMID 34829712, 2021). "There are known observations of the relationship between the protective effect of catalase dependent on estrogens, e.g., in the case of coronary diseases." (PMID 38534743, 2024). "In a meta-analysis of observational studies, lower levels of SOD, CAT and GPx were found in persons with coronary heart disease (CHD)." (PMID 33803155, 2021). "The pooled odds ratio for coronary heart disease was significantly and inversely associated with a 1-standard deviation increase in GPx (0.51, 95% CI 0.35 to 0.75), SOD (0.48, 95% CI 0.32 to 0.72), and catalase (0.32, 95% CI 0.16 to 0.61)." (PMID 34829712, 2021). "Studies investigating the role of CAT polymorphisms in cardiovascular disease are also scarce; however, CAT rs1001179 was not a risk factor for coronary artery disease in a recent study." (PMID 33425072, 2020). "For instance, in the early stages of coronary artery disease the amount of SOD and CAT become elevated to protect and prevent lipid peroxidation whereas they decrease significantly with the worsening of the disease." (PMID 30995791, 2019).
iron deficiency (16 papers, 2012 to 2025). "In current results, the activities of tSOD, tGPx, and CAT declined in rats exposed to CdCl2 due to the ability of Cd to interact with iron, which led to iron deficiency because iron is considered a structural building block of the CAT active site." (PMID 38370884, 2023). "By also affecting SERCA activity, iron deficiency is able to produce a stable change to CaT amplitude and, hence, contraction." (PMID 30779710, 2019). "Iron deficiency also affects the production of other iron-containing proteins, such as cytochrome, myoglobin, catalase, and peroxidase." (PMID 26527217, 2015). "Indeed, reduced catalase activity and increased oxidative stress have been reported in patients with iron deficiency, and studies in iron-depleted cells and mouse models have also demonstrated increased oxidative damage in tissues." (PMID 41199868, 2025). "Iron deficiency affects iron-porphyrin enzymes such as peroxidases and catalase." (PMID 35631204, 2022). "In addition, previous studies reported that iron-containing enzymes (superoxide dismutase, catalase, and glutathione peroxidase) were involved in the detoxification of ROS, and iron deficiency is believed to be dependent on the type and quantity of mugineic acid." (PMID 36986990, 2023). "Therefore, a decreased catalase activity could be anticipated in iron deficiency and has been corroborated in this study, in agreement with other works." (PMID 26527217, 2015). "After 7 d of iron deficiency, POD and CAT activities were significantly increased in the three soybean complexes compared with the control (p<0.01)." (PMID 38250443, 2023). "As an important cofactor in the synthesis of many enzymes, iron deficiency leads to a decrease in antioxidant activities, such as POD and CAT, and causes plant cells to accumulate more H2O2." (PMID 36077250, 2022). "Many DEGs are linked to antioxidant enzyme activity, such as peroxidase (POD), superoxide dismutase (SOD), catalase (CAT), and ascorbate peroxidase (APX), were discovered during iron deficiency stress." (PMID 35371147, 2022). "Under iron deficiency, plants can reduce or remove the active oxygen in the cell to avoid the harm caused by the accumulation of ROS through the synergistic action of the SOD, CAT, and POD." (PMID 38250443, 2023). "Similarly, melatonin treatment reduces hydrogen peroxide, MDA, and electrolyte leakage and increases the antioxidant enzyme catalase (CAT) level under individual and combined salt and iron deficiency." (PMID 37108609, 2023).